RNY1P12 (RNY1 pseudogene 12)
Gene: Miscellaneous RNA gene on chromosome 3 (101,662,060 to 101,662,164, reverse strand). Ensembl gene ENSG00000201121.
Homologues: Orthologues: chimpanzee Y_RNA (100% identical), guinea pig Y_RNA (90% identical), macaque Y_RNA (88% identical). Paralogues in human: RNY1 (92% identical), Y_RNA (90% identical), RNY1P11 (90% identical), Y_RNA (89% identical), RNY1P10 (88% identical), Y_RNA (88% identical), RNY1P8 (87% identical), Y_RNA (87% identical), Y_RNA (86% identical), Y_RNA (85% identical), Y_RNA (84% identical), RNY1P5 (83% identical), and 96 more.